UQCRB (ubiquinol-cytochrome c reductase binding protein)
Description:
Component of the ubiquinol-cytochrome c oxidoreductase, a multisubunit transmembrane complex that is part of the mitochondrial electron transport chain which drives oxidative phosphorylation. The respiratory chain contains 3 multisubunit complexes succinate dehydrogenase (complex II, CII), ubiquinol-cytochrome c oxidoreductase (cytochrome b-c1 complex, complex III, CIII) and cytochrome c oxidase (complex IV, CIV), that cooperate to transfer electrons derived from NADH and succinate to molecular oxygen, creating an electrochemical gradient over the inner membrane that drives transmembrane transport and the ATP synthase. The cytochrome b-c1 complex catalyzes electron transfer from ubiquinol to cytochrome c, linking this redox reaction to translocation of protons across the mitochondrial inner membrane, with protons being carried across the membrane as hydrogens on the quinol. In the process called Q cycle, 2 protons are consumed from the matrix, 4 protons are released into the intermembrane space and 2 electrons are passed to cytochrome c.
Synonyms: UQBP; QP-C; QCR7; UQCR6; MC3DN3; QPC; UQBC; UQPC
Tractability: Small molecule: a structure with a bound ligand is known. Antibody: UniProt places it where antibodies can reach, with medium confidence. PROTAC: ubiquitination databases record sites on it; its protein half-life has been measured; a small molecule that binds it is known.
Target class: Transmembrane 1-electron transfer carriers; Transporter
Gene: Protein-coding gene on chromosome 8 (96,222,947 to 96,235,564, reverse strand). Ensembl gene ENSG00000156467.
Subcellular location: Mitochondrion inner membrane
Pathways (Reactome):
Metabolism: Complex III assembly; Respiratory electron transport
Gene Ontology:
Molecular function: protein binding
Biological process: aerobic respiration; cellular respiration; mitochondrial electron transport, ubiquinol to cytochrome c; oxidative phosphorylation
Cellular component: mitochondrial inner membrane; mitochondrion; respiratory chain complex III; respiratory chain complex; membrane
Genetic constraint (gnomAD): Loss-of-function variants: 12 observed, 20.42 expected, observed/expected ratio (o/e) 0.59, 90% interval 0.38 to 0.95. The upper end of that interval is the gene's LOEUF score, 0.95, which puts it in group 4 of 6, group 1 being the genes least tolerant of losing a copy. Missense variants: 142 observed, 138.26 expected, observed/expected ratio (o/e) 1.03, 90% interval 0.89 to 1.18. Synonymous variants: 39 observed, 44.65 expected, observed/expected ratio (o/e) 0.87, 90% interval 0.68 to 1.14.
Gene-disease validity (ClinGen):
ClinGen rates the evidence that UQCRB causes each of these diseases.
mitochondrial disease (autosomal recessive): Limited.
Homologues: Orthologues: guinea pig UQCRB (91% identical), mouse Uqcrb (87% identical), pig UQCRB (87% identical), rabbit UQCRB (87% identical), rat Uqcrb (86% identical), macaque UQCRB (76% identical), zebrafish uqcrb (72% identical), tropical clawed frog UQCRB (71% identical), Drosophila melanogaster UQCR-14 (56% identical), Drosophila melanogaster UQCR-14L (55% identical), Caenorhabditis elegans T02H6.11 (39% identical).
Diseases named in the same sentence as UQCRB in open-access papers:
UQCRB is named in the same sentence as 37 diseases in open-access papers, as found by Europe PMC text mining. Sharing a sentence is not in itself a finding about the gene and the disease. The quoted sentences say what the papers report.
colon carcinoma (5 papers, 2018 to 2024). "Collectively, our study showed that increasing levels of mROS caused by the overexpression of UQCRB in human colon carcinoma HCT116 cells could be linked to autophagy for cell survival." (PMID 35454800, 2022). "Studies suggest that UQCRB overexpression‐induced elevated mitochondrial ROS levels in human colon cancer cells induce autophagy and that UQCRB is a new molecular prognostic biomarker of colorectal cancer." (PMID 39584783, 2024). "When the cells were treated with the UQCRB inhibitor A1938, proliferation was also inhibited in a dose-dependent manner in the mutant UQCRB-expressing cells and colon cancer cells." (PMID 32071343, 2020). "Collectively, we identified that the increasing level of mROS by the overexpression of UQCRB in human colon carcinoma could link to autophagy for colorectal cancer survival." (PMID 35454800, 2022). "To further investigate the relationship between hsa-miR-10a-5p and UQCRB, we analyzed hsa-miR-10a-5p levels in cell lines of UQCRB expressing cancer, namely, HepG2 (human hepatocellular carcinoma), PC3 (human prostate cancer) and HCT116 cells (human colon cancer cell)." (PMID 30120311, 2018).
colorectal cancer (5 papers, 2018 to 2025). A primary or metastatic malignant neoplasm that affects the colon or rectum. "Methylation of a nuclear gene that encodes a mitochondrial protein (UQCRB) has been identified as a potential biomarker in colorectal cancers." (PMID 30619609, 2018). "Furthermore, these findings suggest that miR-4435 is related to an oncogenic function in UQCRB related disease, CRC, and that effects migration and invasion on mutant UQCRB-expressing cell lines and colorectal cancer cell." (PMID 32071343, 2020). "Ubiquinol-cytochrome c reductase (UQCRB), a subunit of the mitochondrial complex III, is highly expressed in tissues from colorectal cancer patients." (PMID 32071343, 2020). "Ubiquinol cytochrome c reductase binding protein (UQCRB) has been reported as a biomarker of colorectal cancer, but its role in tumor growth has not been clarified." (PMID 35454800, 2022).
hepatocellular carcinoma (5 papers, 2018 to 2022). A malignant tumor that arises from hepatocytes. "UQCRB variants play important roles in various cancers, such as hepatocellular carcinoma, ovarian cancer, and pancreatic ductal adenocarcinoma." (PMID 35454800, 2022). "To test this possibility, we measured the levels of ATP and the abundance of proteins CYCS, NDUFB6, and UQCRB in Hepa1–6 cells (mouse hepatoma cells)." (PMID 32546794, 2020). "There are examples of UQCRH levels correlating with other CIII subunits, such as UQCRB, UQCRC2 and CYC1 expression in hepatocellular carcinoma." (PMID 34750991, 2021).
glioblastoma (3 papers, 2022 to 2025). The most malignant astrocytic tumor (WHO grade IV). "Both COX5A and the gene encoding another subunit of complex III, UQCRB, are downregulated in glioblastoma patients compared to healthy individuals." (PMID 36142793, 2022).
glioma (3 papers, 2019 to 2024). A benign or malignant brain and spinal cord tumor that arises from glial cells (astrocytes, oligodendrocytes, ependymal cells). "CMC1, COX20, and UQCRB are other mitochondrial genes specifically involved in the prognosis of glioma." (PMID 39012280, 2024).
atherosclerosis (2 papers, 2014 to 2025). A disease characterized by the build-up of fatty material and calcium deposition in the arterial wall resulting in partial or complete occlusion of the arterial lumen. "Notably, UQCRB is significantly downregulated in atherosclerosis, a major risk factor for IS." (PMID 41305834, 2025).
hypoglycaemia (2 papers, 2017 to 2020). "A girl with a mutation in the UQCRB gene showed hypoglycemia and lactic acidosis during a metabolic crisis as a baby." (PMID 32071343, 2020). "These individuals with mutations in UQCRB, UQCRC2, and CYC1 presented with neonatal or early infancy onset, recurrent metabolic crises with elevated lactate and hypoglycaemia, from which they completely and quickly recovered with intravenous glucose." (PMID 28804536, 2017).
Allergy (1 paper, 2019). An allergy is an immune response or reaction to substances that are usually not harmful. "Notwithstanding, the present data indicate that the novel allergen Der p 24, a UQCRB protein homolog, represents a good candidate for HDM allergy diagnosis and therapy applications owing to its specific allergenic sequences." (PMID 31139345, 2019).
liver cancer (1 paper, 2018). An epithelial or non-epithelial malignant neoplasm that arises from the liver. "Additionally, treatment with A1938, a UQCRB inhibitor, restored hsa-miR-10a-5p expression levels in liver cancer cell lines." (PMID 30120311, 2018).
melanoma (1 paper, 2025). A malignant, usually aggressive tumor composed of atypical, neoplastic melanocytes. "For two ASEs, we detected at least one atypical isoform in both BC and melanoma: one occurring in UQCRB and another in the protein phosphatase 1 catalytic subunit beta (PPP1CB) that was detected in up to 30 patients." (PMID 41273175, 2025).
osteosarcoma (1 paper, 2024). A usually aggressive malignant bone-forming mesenchymal neoplasm, predominantly affecting adolescents and young adults. "According to the Kaplan-Meier (KM) survival analysis of 8 modeled genes, elevated expression levels of COL5A2, COX6A2, UQCRB, SFXN4, FAM162A and MAFF sharply shortened the survival time of osteosarcoma patients." (PMID 39569192, 2024). "Multivariate Cox regression analysis confirmed that these 8 identified genes, including 2 protective elements (SQOR and PFKFB2) and 6 hazardous factors (MAFF, COL5A2, FAM162A, UQCRB, SFXN4, and COX6A2), could independently predict the overall survival of osteosarcoma samples." (PMID 39569192, 2024).
tumor (10 papers, 2012 to 2025). "Moreover, synthetic small molecules that specifically target UQCRB were also designed and showed an anti-angiogenic effect, causing repression of tumor growth in mouse xenograft models." (PMID 34987545, 2021). "Interestingly, for both UQCRB polymorphisms, the TT carriers were more likely to develop tumours in the colon than in the rectum, with ORs of 2.02 (95% CI 1.24–3.28) for rs7836698 (TT vs. CC) and 1.74 (95% CI 1.08–2.78) for rs10504961 (TT vs. CC)." (PMID 22545919, 2012). "Small molecules that specifically regulate the function of UQCRB could suppress tumor growth by regulating the functional links between UQCRB, mROS, and autophagy." (PMID 35454800, 2022). "Novel therapies addressing this tumor subset are urgently needed, and targeting UQCRB might be an option worth investigating, at least for some forms of these tumor types." (PMID 36354671, 2022). "More specifically, high mRNA expression levels of CYC1 (Cytochrome C1) and UQBP (Ubiquinol-Cytochrome C Reductase Binding Protein), key components of complex III, are both associated with significantly reduced progression-free survival (i.e., higher tumor recurrence)." (PMID 27136895, 2016). "Therefore, UQCRB inhibitors could be a novel therapeutic strategy for regulating autophagy in the tumor environment." (PMID 35454800, 2022). "SCENIC predicted the top 4 transcription factors that differed expressed most between the two subgroups of tumour cells: SAP30, UQCRB, ZBTB33 and ZNF165." (PMID 40830065, 2025).
cancer (5 papers, 2018 to 2024). A tumor composed of atypical neoplastic, often pleomorphic cells that invade other tissues. "Overexpression of UQCRB causes the production of mROS, and inhibition of UQCRB decreases mROS generation in various cancer cell lines, including HT1080, HepG2, and U87MG." (PMID 35454800, 2022). "Although A1938 has been shown to have a therapeutic value to treat cancer cells particularly overexpressing UQCRB protein, high micromolar levels of A1938 were needed in our previous studies." (PMID 35454800, 2022). "For these reasons, we investigated whether the UQCRB inhibitor A1938 could affect the growth of cancer cells by inhibiting autophagy." (PMID 35454800, 2022). "Because the basal level of ROS has been shown to be increased in cancer cells when compared with normal cells, we investigated whether the inhibition of UQCRB regulates ROS generation in HCT116 cells." (PMID 35454800, 2022). "In addition, hybrid cells displayed upregulated expression of ubiquinol-cytochrome c reductase binding protein (UQCRB), which has been shown to promote angiogenesis and cancer cell survival, that may facilitate hybrid cell dissemination into peripheral blood." (PMID 38106024, 2023).
mitochondrial disease (1 paper, 2021). "Many mitochondrial disease-related altered proteins also formed part of the energy network (DLD, NDUFA4, NDUFB5, NDUFB6, NDUFB9, NDUFS1, NDUFA12 and UQCRB) and belong to respiratory electron transport with the exception of DLD, which belongs to the TCA cycle." (PMID 34576238, 2021).
UQCRB also shares sentences with these, for which no sentence is quoted: Alzheimer disease (3 papers); Parkinson disease (3); breast carcinoma (2); cardiovascular diseases (1); COVID-19 (1); epilepsy (1); escherichia coli infection (1); Hepatic steatosis (1); Huntington disease (1); Hypertension (1); infection (1); lactic acidosis (1); metastatic tumors (1); Miscarriage (1); neurodegenerative disease (1); non-alcoholic fatty liver disease (1); ovarian carcinoma (1); pancreatic cancers (1); pancreatic ductal adenocarcinoma (1); prostate carcinoma (1); steatosis (1); Stroke (1); systemic candidiasis (1).